ARPC5 (actin related protein 2/3 complex subunit 5)
Description:
Component of the Arp2/3 complex, a multiprotein complex that mediates actin polymerization upon stimulation by nucleation-promoting factor (NPF). The Arp2/3 complex mediates the formation of branched actin networks in the cytoplasm, providing the force for cell motility. In addition to its role in the cytoplasmic cytoskeleton, the Arp2/3 complex also promotes actin polymerization in the nucleus, thereby regulating gene transcription and repair of damaged DNA. The Arp2/3 complex promotes homologous recombination (HR) repair in response to DNA damage by promoting nuclear actin polymerization, leading to drive motility of double-strand breaks (DSBs).
Synonyms: p16-ARC; ARC16; dJ127C7.3; IMD113
Tractability: Small molecule: a structure with a bound ligand is known. Antibody: its Gene Ontology location is reachable by antibodies, with high confidence; the Human Protein Atlas places it where antibodies can reach. PROTAC: UniProt records ubiquitination sites on it; ubiquitination databases record sites on it; its protein half-life has been measured.
Gene: Protein-coding gene on chromosome 1 (183,620,846 to 183,635,783, reverse strand). Ensembl gene ENSG00000162704.
Subcellular location: Cytoplasm, cytoskeleton; Cell projection; Nucleus
Subcellular location (Human Protein Atlas): Cell Junctions; Cytosol; Plasma membrane; Vesicles
Pathways (Reactome):
Immune System: Neutrophil degranulation; Regulation of actin dynamics for phagocytic cup formation
Developmental Biology: EPHB-mediated forward signaling
Disease: FCGR3A-mediated phagocytosis
Signal Transduction: RHO GTPases Activate WASPs and WAVEs
Vesicle-mediated transport: Clathrin-mediated endocytosis
Gene Ontology:
Molecular function: actin filament binding; protein binding; structural constituent of cytoskeleton; protein-macromolecule adaptor activity
Biological process: Arp2/3 complex-mediated actin nucleation; cell migration; actin cytoskeleton organization; regulation of actin filament polymerization
Cellular component: Arp2/3 protein complex; extracellular exosome; focal adhesion; nucleus; actin cytoskeleton; cortical cytoskeleton; cytoplasm; cytosol; extracellular region; ficolin-1-rich granule lumen; secretory granule lumen; site of double-strand break; cytoskeleton; lamellipodium
Genetic constraint (gnomAD): Loss-of-function variants: 3 observed, 10.69 expected, observed/expected ratio (o/e) 0.28, 90% interval 0.13 to 0.73. The upper end of that interval is the gene's LOEUF score, 0.73, which puts it in group 2 of 6, group 1 being the genes least tolerant of losing a copy. Missense variants: 133 observed, 191.65 expected, observed/expected ratio (o/e) 0.69, 90% interval 0.6 to 0.8. Synonymous variants: 84 observed, 75.15 expected, observed/expected ratio (o/e) 1.12, 90% interval 0.94 to 1.34.
Homologues: Orthologues: chimpanzee ARPC5 (100% identical), rat Arpc5 (100% identical), guinea pig ARPC5 (99% identical), mouse Arpc5 (99% identical), pig ARPC5 (99% identical), dog ARPC5 (99% identical), zebrafish arpc5a (83% identical), zebrafish arpc5b (82% identical), tropical clawed frog arpc5 (66% identical), Drosophila melanogaster Arpc5 (53% identical), Caenorhabditis elegans arx-7 (44% identical), macaque ARPC5 (39% identical), and 1 more. Paralogues in human: ARPC5L (69% identical).
Diseases named in the same sentence as ARPC5 in open-access papers:
ARPC5 is named in the same sentence as 41 diseases in open-access papers, as found by Europe PMC text mining. Sharing a sentence is not in itself a finding about the gene and the disease. The quoted sentences say what the papers report.
melanoma (9 papers, 2014 to 2025). A malignant, usually aggressive tumor composed of atypical, neoplastic melanocytes. "Our results show that the ArpC5 isoform is clearly associated with more prolific actin assemblies in lamellipodia of Rat2 fibroblasts and B16-F1 melanoma cells." (PMID 36662867, 2023). "ARPC5 mediated melanoma cell migration and is critical for maintenance of YAP-dependent melanoma cell adhesion." (PMID 37231521, 2023). "In melanoma, ARPC5 can be a specific target of Yes-associated protein 1 (YAP) and promote melanoma cell progression, survival, and invasion." (PMID 36605483, 2023). "This notwithstanding, ArpC5/5L isoforms showed cell type–specific differences in VACV actin tail formation in B16-F1 melanoma cells, Rat2 fibroblast, and HeLa cells." (PMID 36662867, 2023). "Several studies demonstrated that ARPC5 contributes to tumor growth or metastasis, including head and neck squamous cell carcinoma, lung squamous cell carcinoma, and melanoma." (PMID 36148220, 2022). "The co-activator YAP, which promotes melanoma growth and spread, controls the Arp2/3 subunit ARPC5." (PMID 41170386, 2025). "More recently, the loss of ARPC5 isoforms in B16 mouse melanoma cells reveals that the absence of ARPC5 but not ARPC5L leads to slower cell migration and reduced Mena/VASP recruitment to the protruding leading edge ARPC5 isoforms." (PMID 37382373, 2023). "In melanoma, YAP drives ARPC5 expression to enhance cell migration, invasion, and focal adhesions." (PMID 36148220, 2022). "To explore the role of the two ArpC5 isoforms in lamellipodia architecture and cell migration, we used a CRISPR-Cas9 knockout (KO) approach to generate B16-F1 mouse melanoma cells lacking either ArpC5 (referred to as C5KO), ArpC5L (C5LKO), or both isoforms (C5/C5LKO)." (PMID 36662867, 2023).
multiple myeloma (7 papers, 2021 to 2023). "In multiple myeloma (MM) cells, ARPC5 expression increased, and high expression of ARPC5 was associated with poor overall survival in MM patients." (PMID 36605483, 2023). "Moreover, bioinformatics analyses have suggested that ARPC5 expression is significantly increased in multiple myeloma (MM) cells compared with normal plasma cells, and high expression of ARPC5 is associated with poor overall survival (OS) in patients with MM." (PMID 36148220, 2022). "Previous studies have demonstrated that the upregulation of ARPC5 can be found in a variety of tumors, such as head and neck squamous cell carcinoma and multiple myeloma, in agreement with our observational results." (PMID 37789267, 2023). "As compared with the less studied ACTR3, the potential of ARPC5 as a prognostic biomarker has been investigated in multiple cancer types such as hepatocellular carcinoma and multiple myeloma." (PMID 34868230, 2021). "ARPC5, actin-related protein 2/3 complex subunit 5, has been revealed to be highly expressed in patients with poor overall survival and could be treated as an independent biomarker for patients with multiple myeloma, consistent with our observations." (PMID 36969740, 2022). "In addition, the ARPC5 high-expression group was associated with poor overall survival compared to that in the ARPC5 low-expression group, and multivariable analysis indicated that ARPC5 was an independent prognostic factor in patients with multiple myeloma (MM)." (PMID 34307456, 2021).
lung squamous cell carcinoma (6 papers, 2021 to 2024). "In addition, ARPC5 was verified to be upregulated in lung squamous cell carcinoma, and its knockdown significantly suppressed cell proliferation." (PMID 37231521, 2023). "Silencing of ARPC5 inhibited cancer cell proliferation in lung squamous cell carcinoma, suggesting that ARPC5 might contribute to lung squamous cell carcinoma development." (PMID 36148220, 2022). "ARPC5 expression was significantly elevated in tumor tissues of lung squamous cell carcinoma." (PMID 36148220, 2022). "ARPC5 may function as an oncogene in the development of lung squamous cell carcinoma (lung SCC) and head and neck squamous cell carcinoma (HNSCC) and contributes to cancer cell migration and invasion, which is directly regulated by miRNA." (PMID 34307456, 2021). "Actin-related protein 2/3 complex subunit 5 (ARPC5), a member of ARP2/3 complex family, is considered to be oncogene in the development of many tumors, such as lung squamous cell carcinoma and hepatocellular carcinoma." (PMID 37231521, 2023).
head and neck squamous cell carcinoma (5 papers, 2021 to 2023). A squamous cell carcinoma that arises from any of the following anatomic sites: lip and oral cavity, nasal cavity, paranasal sinuses, pharynx, larynx, and salivary glands. "ARPC5 served as tumor promoter in head and neck squamous cell carcinoma, which silencing could restrain cell migration and invasion to hinder cancer process." (PMID 37231521, 2023). "In head and neck squamous cell carcinoma (HNSCC), the expression of ARPC5 was significantly higher in cancerous tissues than in non-cancerous tissues." (PMID 36605483, 2023).
hepatocellular carcinoma (5 papers, 2021 to 2025). A malignant tumor that arises from hepatocytes. "Our previous study also suggested that the higher ARPC5 expression has significantly poor OS and acts as an independent factor in predicting poor prognosis of hepatocellular carcinoma (HCC) patients." (PMID 36148220, 2022).
Immunodeficiency (4 papers, 2023 to 2025). Failure of the immune system to protect the body adequately from infection, due to the absence or insufficiency of some component process or substance. "Patients with loss-of-function mutations in the ARPC5 subunit of the Arp2/3 complex develop inflammation and immunodeficiency after birth, leading to early mortality." (PMID 41231985, 2025). "In this respect, mutations in ARPC1B, ARPC4 and ARPC5, which encode components of the Arp2/3 complex, have been identified as the cause of several genetic disorders, characterised by either immunodeficiency and thrombocytopenia or microcephaly and neurodevelopmental defects." (PMID 40368919, 2025). "In the modulation of the inflammatory microenvironment, multiple subunits contribute to pathological processes through distinct mechanisms: Loss-of-function mutations in the ARPC5 subunit trigger postnatal inflammation and immunodeficiency in mice, ultimately leading to early lethality." (PMID 41332982, 2025). "We show that human ARPC5 deficiency cannot be compensated for by the presence of wild-type (WT) ARPC5L, and leads to a syndrome featuring immune disease, multiple congenital anomalies and early postnatal death." (PMID 37382373, 2023). "Moreover, our observations add ARPC5 to the list of genes that should be considered when patients present with syndromic early-onset immunodeficiency, particularly if recessive inheritance is suspected." (PMID 37382373, 2023).
lung cancer (3 papers, 2021 to 2024). A malignant neoplasm involving the lung. "Their study detected 15 Chr9 proteins highly selective for lung cancer in comparison to healthy lung tissue (i.e., RAD23B, RPS6, ARPC5)." (PMID 38539567, 2024). "Candidate genes ACTR3, ARPC5, and HNRNPK were highly expressed in almost all types of lung cancer immune cells, while RAB13, PA2G4, and WDR12 were found to be less abundant in the majority of myeloid populations in lung cancer." (PMID 34868230, 2021).
Thrombocytopenia (3 papers, 2023 to 2025). A reduction in the number of circulating thrombocytes. "Thrombocytopenia in ARPC5 deficiency is probably another multifactorial complication in this disease." (PMID 37349293, 2023). "Through whole-exome sequencing, we identified a biallelic ARPC5 frameshift variant in a female child who presented with recurrent infections, multiple congenital anomalies, diarrhea and thrombocytopenia, and suffered early demise from sepsis." (PMID 37382373, 2023).
Autoimmunity (2 papers, 2023 to 2025). The occurrence of an immune reaction against the organism's own cells or tissues. "Here the authors describe biallelic null mutations in the ARPC5 subunit of Arp2/3 that disrupt actin function and cytokine signaling, causing infections, autoimmunity, inflammation and dysmorphisms." (PMID 37349293, 2023). "We describe the first cases of germline biallelic null mutations in ARPC5, part of the Arp2/3 actin nucleator complex, in two unrelated patients presenting with recurrent and severe infections, early-onset autoimmunity, inflammation, and dysmorphisms." (PMID 37349293, 2023).
liver cancer (2 papers, 2023). An epithelial or non-epithelial malignant neoplasm that arises from the liver. "LncRNA DSCR8 promotes the proliferation of liver cancer cells and inhibits apoptosis via the miR-22-3p/ARPC5 axis." (PMID 37858131, 2023).
Sepsis (2 papers, 2023 to 2025). Sepsis is defined as life-threatening organ dysfunction caused by a dysregulated host response to infection. "More recently, we and others have found that loss of the ARPC5 subunit of the Arp2/3 complex results in intestinal inflammation, recurrent infections, and sepsis, leading to early mortality." (PMID 41231985, 2025). "More recently, loss-of-function mutations in ARPC5 have also been reported to result in gastrointestinal conditions and increased susceptibility to infection, leading to sepsis and early death." (PMID 41231985, 2025).
Anxiety (1 paper, 2021). Intense feelings of nervousness, tension, or panic often arise in response to interpersonal stresses. "The results indicated that Atp6v1f, Arpc5, Adcyap1r1, Ndufb6, and Psmc6 were distinctly dysregulated in the hypothalamus of the depression-susceptible group, while Gys1, Pgp, Klc1, Chka, Ncstn, Ndufa6, and Kyat1 were distinctly dysregulated in the anxiety-susceptible group." (PMID 33737865, 2021).
cerebral infarction (1 paper, 2025). An ischemic condition of the brain, producing a persistent focal neurological deficit in the area of distribution of the cerebral arteries. "In a mouse model experiment, the upregulated expression of ARPC5 was found to have a protective effect on neuronal cells during cerebral infarction, potentially through endocytosis mechanisms." (PMID 40303468, 2025).
cholangiocarcinoma (1 paper, 2022). A carcinoma that arises from the intrahepatic biliary tree (intrahepatic cholangiocarcinoma) or from the junction, or adjacent to the junction, of the right and left hepatic ducts (hilar cholangiocarcinoma). "In our analyses, we found that the most frequent mutation type of ARPC5 was “Amplification” mutation and the frequency of “Amplification” was varied among different cancer types, which was most commonly observed in cholangiocarcinoma, invasive breast carcinoma, and HCC." (PMID 36148220, 2022).
colitis (1 paper, 2021). Inflammation of the colon. "Of note, arpin protein was also significantly downregulated in colons from mice with DSS-induced colitis, whereas ArpC5 levels were again unaltered." (PMID 34012961, 2021).
colorectal adenocarcinoma (1 paper, 2022). The most common type of colorectal carcinoma. "A total of 961, 500, and 500 tumors as well as 836, 413, and 434 paracarcinoma normal tissues from 993, 509, and 509 subjects with colorectal adenocarcinoma were informative for CORO1C, RAD23B, and ARPC5, respectively." (PMID 35589723, 2022).
depression (1 paper, 2021). "The expressions of Atp6v1f, Arpc5, Ndufb6, and Psmc6 were significantly down-regulated while Adcyap1r1 was up-regulated in the depression-susceptible group compared with the control group." (PMID 33737865, 2021).
glioma (1 paper, 2023). A benign or malignant brain and spinal cord tumor that arises from glial cells (astrocytes, oligodendrocytes, ependymal cells). "Our study revealed that the high expression level of ARPC5 may serve as a promising prognostic biomarker and be associated with tumor immunity in glioma." (PMID 37789267, 2023). "However, the association between ARPC5 expression and clinical significance in glioma is still unclear." (PMID 37789267, 2023). "Our results revealed that there was a significant positive correlation between ARPC5 expression and T cells in 10 glioma samples." (PMID 37789267, 2023). "Our results also showed that ARPC5 expression is positively correlated with most immune markers in glioma." (PMID 37789267, 2023). "In experimental analysis, we found that ARPC5 was significantly overexpressed in gliomas and closely correlated with patient prognosis and CD3 expression." (PMID 37789267, 2023). "Then, we further used the glioma chip and found that the expression of ARPC5 is closely related to the prognosis of glioma patients." (PMID 37789267, 2023). "In this research, we first analyzed the expression of ARPC5 in glioma on account of the TCGA database, which verified that ARPC5 was upregulated in glioma patients." (PMID 37789267, 2023). "First, we detected the protein expression level of ARPC5 in glioma cell lines by Western blot, and found that ARPC5 expression in LN229 and U251 cells was significantly higher than that in other glioma cell lines, which was suitable for subsequent experiments." (PMID 37789267, 2023). "Although it has been elucidated that ARPC5 expression was abnormally increased in glioma and closely related to different clinical characteristics, the prognostic values of ARPC5 in glioma patients were still unclear." (PMID 37789267, 2023). "We calculated the relationship between immune microenvironment and ARPC5 expression in glioma via the estimate algorithm, and the results found that high expression of ARPC5 was positively correlated with immune score." (PMID 37789267, 2023). "In our study, we explored the expression and clinical significance of ARPC5 in gliomas by integrating multiple databases and in-depth assessing its impact glioma." (PMID 37789267, 2023). "ROC curve, univariate and multivariate analyses, and a clinical correlation nomogram were performed to further indicate that ARPC5 was an important predictor of glioma." (PMID 37789267, 2023). "Our data first showed that high expression of ARPC5 was positive associated with immune score, stromal score and TMB in glioma." (PMID 37789267, 2023). "Collectively, we found that ARPC5 is overexpressed in gliomas, and its expression is closely related to various clinical characteristics of glioma patients." (PMID 37789267, 2023). "We further studied the distribution of ARPC5 expression in different types of gliomas by analyzing single-cell data." (PMID 37789267, 2023). "GSEA was conducted to investigate signal pathways in the development of glioma and compare datasets with low and high ARPC5 expression." (PMID 37789267, 2023). "Meanwhile, further studies showed that high expression of ARPC5 was related to the poor immunotherapy efficacy of glioma." (PMID 37789267, 2023). "In general, the results above suggested that ARPC5 was abnormally expressed in gliomas." (PMID 37789267, 2023). "Based on the TCGA, GEO, HPA, and UALCAN database, we determined the expression of ARPC5 in glioma." (PMID 37789267, 2023). "In addition, we evaluated glioma and near-by tissues of 10 patients by immunohistochemistry tests, and the results indicated that ARPC5 expression was obviously higher in glioma tissues." (PMID 37789267, 2023). "The present findings also indicated that ARPC5 may regulate glioma development by participating in tumor immunity." (PMID 37789267, 2023). "The researches preliminarily suggest that ARPC5 could act as a potential prognostic target in glioma." (PMID 37789267, 2023).